VIM (vimentin)
Diseases named in the same sentence as VIM in open-access papers (continued):
Sharing a sentence is not in itself a finding about the gene and the disease.
tumor (continued). "Immunofluorescence (IF) analysis showed good concordance with the original tumor with NUCOLL43 positive for vimentin and pan‐cytokeratin at early and late passage." (PMID 30109783, 2018). "EpCAMlow/-/vimentin+ cells lined up as agglomerates within tumor protrusions and as islands of vimentin+ cells at the edge of large tumor areas (central panel)." (PMID 30275505, 2018). "In line with previous findings on HNSCC, 24 out of 31 SOX2negtive tumors showed high expression of vimentin in tumor cells, indicating a more mesenchymal phenotype." (PMID 29596469, 2018). "Overexpression of CEACAM5 led to increased tumor growth in lungs, decreased expression of vimentin at the protein level, and decreased phosphorylation of p38." (PMID 29736411, 2018). "This tumour has a dual mesenchymal and epithelial differentiation potential, and hence shows positivity to both vimentin and keratin." (PMID 29609578, 2018). "Immunolabeling of CD34 and Vimentin in the tumor sections revealed that ECs and fibroblast cells were less numerous in AKT/Yap/Cre lesions." (PMID 29545603, 2018). "These molecular networks with reported functionality in tumor progression and treatment resistance prompted us to investigate protein co-expression levels and patterns of Sox2, EpCAM and vimentin in HNSCC." (PMID 30275505, 2018). "High levels of the AMAP1 expression among PyMT-tumor cells were frequently correlated with loss of the epithelial marker CK8 and also with expression of the mesenchymal marker vimentin both at the primary sites and at sites of the lung metastases." (PMID 29329590, 2018). "EMT is an enabling step towards tumor metastasis, and is characterized by upregulation of mesenchymal markers such as intermediate filament protein vimentin and reduced expression of the normal epithelium adhesion protein E-cadherin." (PMID 29245898, 2017). "Consistent with the less motile phenotype, the protein level of epithelial cell marker E-cadherin was significantly elevated in 64B-treated tumor cells, accompanied by a reduction in vimentin and Snail1, two mesenchymal markers." (PMID 29245898, 2017). "In our study, clinicopathologic parameters were evaluated and the expression of EMT markers E-cadherin and vimentin in tumor tissue was detected by immunohistochemistry (IHC)." (PMID 28744307, 2017). "Metastasizing tumor cells show increased expression of the intermediate filament (IF) protein vimentin, which has been used to diagnose invasive tumors for decades." (PMID 28117759, 2017). "In contrast, E-cadherin was expressed strongly in epithelial cells located in the tumor proper, in between the vimentin-positive borders, in 468-WT, 468-shSCR, 468-pcDNA3, and 468-CDH1 tumors." (PMID 28750639, 2017). "EMT is characterized by the down-regulation of E-cadherin, an epithelial marker; the up-regulation of mesenchymal markers, such as Vimentin, N-cadherin, and Snail; and the potently enhanced ability of tumor cell invasion and metastasis." (PMID 28356132, 2017). "L1CAM expression was strongly associated with percentage of vimentin expressing tumor cells (P = 0.003), and expression of both L1CAM and vimentin indicated a subgroup with the highest change of recurrence (HR 3.15, 95% CI 1.25 – 7.92, P = 0.015)." (PMID 29152102, 2017). "Conversely, vimentin expression was repressed in MRPS23 knockdown tumours compared with shCtrl-infected samples." (PMID 29069745, 2017). "In the current study, we found a reduction in the expression of K5/K14 pair upon vimentin downregulation, perhaps mediated through ΔNp63, resulting in a more differentiated phenotype of the tumor cell." (PMID 28225793, 2017).
tumor (continued). "The results showed that the expression of N-cadherin and vimentin in subcutaneous tumor was significantly lower than that in the sh-NC group, while E-cadherin was upregulated." (PMID 28060737, 2017). "The tumor showed positive immunostaining for Vimentin, CD31, CK7, D2–40, c-MYC, Ki67, focal positivity for PanCK, and negative immunostaining for Factor VIII, CD34, WT1, CK5/6, Calretinin, EMA, HBME-1, CEA, p63, EpCAM, Bcl-2, TTF1 and Thyroglobulin." (PMID 28810922, 2017). "The results showed frequent co-incidence of low E-cadherin expression and high N-cadherin and vimentin expression in tumor tissues highly expressing miR-4775." (PMID 28095858, 2017). "On the other hand, evidence supports that vimentin is a crucial cytoskeletal component of motile mesenchymal cells, including epithelium-derived metastatic tumor cells." (PMID 29234409, 2017). "Next, protein level of N-cadherin, Vimentin increased in HS-746T/FAM83D cells indicating FAM83D overexpression promotes epithelial-mesenchymal transition (EMT) in tumor progression." (PMID 29088801, 2017). "The proposed technique exploited a novel monoclonal antibody specifically recognizing a tumour-surface vimentin, thus discriminating cancer cells from mononuclear blood cells that express intracellular vimentin." (PMID 29246026, 2017). "For survival analysis, patients were stratified according to L1CAM expression and percentage of vimentin expressing tumor cells." (PMID 29152102, 2017). "Given that these cells expressed human vimentin, it appeared that these giant cells were of tumor origin." (PMID 28750639, 2017). "Accordingly, we employed immunohistochemical staining (IHC) to analyze the expression of E-cadherin, N-cadherin, and vimentin in tumor tissue from 544 CRC patients." (PMID 28095858, 2017). "In the transplanted tumor, compared with the control group, E-cadherin was upregulated in the high-dose group, low-dose group, and 5-FU group, while the level of N-cadherin, vimentin, TGF-β, Snail, and Slug went downwards." (PMID 28539961, 2017). "In this study, we found that oleate-induced PTX3 enhanced vimentin expression to promote tumor invasion." (PMID 28489600, 2017). "Vimentin, ZEB1, and Slug genes linked with the EMT process are essential for tumor cells to exhibit survival capacity." (PMID 29038587, 2017). "The extent of in vivo vimentin expression across the various tumor groups strongly correlated with E-cadherin status." (PMID 28750639, 2017). "Particularly, KISS1 is able to inhibit EMT by via suppressing N-cadherin and vimentin, and increasing E-cadherin expression then diminish tumor cell migration and invasion motility." (PMID 28973968, 2017). "Furthermore, vimentin expression has frequently been detectable in the majority of finger-like invasive fronts of tumors and may be associated with the metastatic conversion of epithelial cells and tumor invasion." (PMID 28057062, 2017). "The tumor measured 5.5X5X4cm; Immunohistochemical stains showed the tumor diffusely positive for inhibin and vimentin." (PMID 28674591, 2017). "In conclusion, our data sheds light on the modulatory role of vimentin in the expression of K5/K14 pair, to fine tune the differentiation switch in favor of tumor progression." (PMID 28225793, 2017). "Dexamethasone enhanced the tumor volume and proliferation, as detected by calipers and Ki67 staining, whereas the expression of vimentin increased and the expression of E-cadherin decreased." (PMID 28981109, 2017). "The restoration of miR-320a expression can suppress GC cell proliferation, migration and invasion by targeting both USP14 and vimentin, which shows that miR-320a acts as a tumor suppressor in GC." (PMID 27448976, 2017). "Vimentin expression was restricted to the invasive edge in the primary tumour where mMDSC infiltration was seen." (PMID 28382931, 2017).
tumor (continued). "For vimentin, serum levels strongly and positively correlated tumour area (r = 0.621, p < 0.05) and tumour grade (r = 0.696, p < 0.05) but showed a weak correlation with tumour stage (r = 0.420, p < 0.05)." (PMID 28616237, 2017). "Consistently, 64B-treated tumor cells display impaired migratory and invasive potential, which is accompanied by decreased protein levels of Snail1 and vimentin as well as an increase in E-cadherin expression." (PMID 29245898, 2017). "Conversely, high expression of E-cadherin and low expression of N-cadherin and vimentin were generally found in tumor tissues of patients with low levels of miR-4775 expression." (PMID 28095858, 2017). "The tumor was positive for human cytokeratin and human vimentin, which suggests that the developed tumor originated from a human source, that is, EBC1 cells." (PMID 28619066, 2017). "As shown in both 4T1/BALB/c and AT-3/C57BL/6J tumour models, mMDSCs induce a strong upregulation of pStat1, pStat3 and pNF-κB as well as enhanced expression of vimentin and twist in tumour cells, while suppressing the pERK1/2 activity." (PMID 28382931, 2017). "Together, our findings provide strong evidence that p62 functions as a tumour metastasis promoter by binding vimentin and promoting its expression." (PMID 28968743, 2017). "Tumour cells expressing E-cadherin were located either in small cell isles in the outer parts of microtissues or in the inner core of vimentin expressing cells." (PMID 28592821, 2017). "More specifically, the overexpression of vimentin in cancer cells is an adverse prognostic factor, correlating with accelerated tumor growth." (PMID 28421110, 2017). "These combined results associate the necrotic interface EMT with HPX and suggest an HPX-independent EMT induction mechanism inducing vimentin at the tumor-stroma border." (PMID 28750639, 2017). "Immunohistochemical analyses showed the tumor stained with vimentin, α-smooth muscle actin, desmin, α1-antitrypsin, and α1-antichymotripsin." (PMID 28144858, 2017). "Results from Western blotting revealed that the protein levels of E-cadherin were upregulated, while the protein levels of vimentin, Snail, Slug, and Twist1 were downregulated in tumor tissues from phenformin-treated mice." (PMID 28947975, 2017). "To assess the EMT status in KPIC tumors, we triple-immunostained the KPIC tumor with E-cadherin, CK and vimentin antibodies." (PMID 28475592, 2017). "The increased in vivo expression of vimentin protein by IHC in 468-shCDH1-B tumors corresponded with upregulated expression of vimentin in matching xenograft tumor RNA." (PMID 28750639, 2017). "Vimentin staining revealed 70% and 79% reductions in overall tumor volumes were observed following treatment with 10 and 100 pmol 6OTD, respectively (top)." (PMID 28620243, 2017). "According to immunohistochemistry, the tumor was positive for vimentin, α1-antitrypsin, and α1-antichymotripsin." (PMID 28144858, 2017). "Vimentin is a predictive biomarker for tumor growth and metastasis, although its significance is limited in TSCC prognosis." (PMID 28570699, 2017). "The EMT markers E-cadherin and vimentin were suppressed and increased, respectively, tumours established by AEG-1-overexpressing SCC15 cells (P < 0.05)." (PMID 29133850, 2017). "Levels of E-cadherin, vimentin as shown in Western blot analysis confirmed the tumor aggressiveness of CL1-5 cells." (PMID 29079814, 2017). "The cells with the high expression of vimentin and E-cadherin suggest that tumor cells are prone to EMT, hence promoting cell invasion and metastasis." (PMID 28358024, 2017). "Vimentin-positive cells (red color) indicating EMT were clearly seen in two distinct areas of the tumor: at regions of the tumor-stroma interface (blue arrows) and along the tumor-necrosis border (yellow arrows)." (PMID 28750639, 2017).
tumor (continued). "MiR-30a has been reported to target EMT-related molecules (such as vimentin or Slug) and to suppress tumor cell migration and invasion in breast cancer as well as other solid cancers." (PMID 29162923, 2017). "LncRNA-Dreh was found to interact with vimentin protein and alter the structure of vimentin intermediate filaments, as well as to repress vimentin protein expression and thus likely functions as a tumour suppressor at least in part through repression of EMT." (PMID 28430163, 2017). "Area under curve (AUC) of ROC of tumor grade was compared with those of CLASP2, E-cadherin and Vimentin mRNA levels in tumor and urine." (PMID 28166762, 2017). "All models closely mirrored parental tumour characteristics although a selective pressure for solid patterns, vimentin expression and EMT was observed in several models." (PMID 28751748, 2017). "The results showed that vimentin mRNA was upregulated in GC tissues compared with adjacent non-tumor tissues." (PMID 27448976, 2017). "Recent studies showed that knockout Vimentin in malignant cells decreased the ability of tumor cell invasion and metastasis." (PMID 28135203, 2017). "In all tri-cultures containing A549, discrimination between E-cadherin expressing tumour and vimentin expressing mesenchymal cells was performed after ten days." (PMID 28592821, 2017). "A significant reduction was observed in the tumor volume in vimentin knockdown as compared its vector control group." (PMID 28225793, 2017). "In primary tumours, the decreased epithelial markers such as E-cadherin, occludin, cytokeratin and the increased mesenchymal markers including N-cadherin, vimentin, snail, slug can promote the tumour invasion and metastasis." (PMID 28548934, 2017). "In 109 FFPE specimens, the percentage of vimentin expressing tumor cells was determined by flow cytometry." (PMID 29152102, 2017). "E-cadherin and Vimentin are proteins in epithelial mesenchymal transition (EMT) which is closely related with tumor invasion and metastasis." (PMID 28135203, 2017). "We observed in the models an expression of Vimentin in tumor cells recapitulating the primary tumor and confirming the glial phenotype of the cancer cells." (PMID 28881750, 2017). "To examine this possibility for nKSCCs, we stained consecutive tumor sections where reduced pan-cytokeratin and E-cadherin levels matched with increased intensity of vimentin." (PMID 29190285, 2017). "When E-cadherin was overexpressed in PC3-TxR and DU145-TxR cells, the expression of Vimentin and Claudin-1 was down-regulated, and tumor cell migration and invasion were inhibited." (PMID 28356132, 2017). "Analysis of tumor cell proliferation in situ by double immunofluorescence using a human-specific vimentin antibody and anti-pSer10 Histone H3, a marker for mitotic cells, did not reveal Nrp1-dependent differences proliferation." (PMID 28938007, 2017). "Together, this suggests that vimentin aids the aggressiveness of the tumor by contributing to the maintenance of a dedifferentiated state of the tumor cell." (PMID 28225793, 2017). "This identification of VIM+/GFAP− cells in the invasive front of this recurrent tumor was in agreement with our observations in the IC-3635PXA tumors." (PMID 29152094, 2017). "The identified differentially expressed proteins were related to mesenchymal cells (vimentin and transglin), or related to tumor aggressiveness with a potential of secretory behavior (e.g. cathepsin B)." (PMID 28670517, 2017). "Tumor cells showed positive immunoreactivity for Vimentin and CD99 and moderate staining for Cam5.2, Syn and PR." (PMID 28472972, 2017). "In contrast, there were significant decreases in the expression levels of N-cadherin and vimentin in L3.6pl and Mia PaCa-2 cells and in tumor tissue compared with vehicle control." (PMID 28404939, 2017). "We investigated the expression of PPA1, E-cadherin, and Vimentin in xenografted mouse EOC tumor slices." (PMID 29100310, 2017).
tumor (continued). "The loss of KLK6 in HNSCC seems to create a mesenchymal-like morphology and accelerated motility of tumor cells with an EMT-phenotype, identified by loss of E-cadherin and prominent induction of vimentin expression in HNSCC cells." (PMID 28671620, 2017). "Lower expression of E-cadherin and overexpression of Vimentin have a closely relationship with tumor progression." (PMID 29383156, 2017). "Cases were subdivided into two groups, based on the 75th percentile (26.1%) of vimentin expressing tumor cells." (PMID 29152102, 2017). "IHC stainings further showed that E-cadherin was decreased, but Vimentin was increased in the transplanted tumor tissues of TNBC cells, which consisted with the in vitro results." (PMID 29228721, 2017). "For vimentin, tumour area strongly correlated with tumour grade (r = 0.696, p < 0.05) but weakly correlated with tumour stage (r = 0.420, p < 0.05)." (PMID 28616237, 2017). "Our results show that the oleate-induced autocrine production of PTX3 enhanced MMP-3 and vimentin expression and tumor/endothelial cell interactions to promote the metastatic seeding of tumor cells in the lungs." (PMID 28489600, 2017). "It was found that molecules related tomesenchymal cells (vimentin and transglin), in addition to those related to tumor aggressiveness with potential secretory behavior (e.g. cathepsin B) were among differentiallyexpressed proteins." (PMID 28670517, 2017). "E-cadherin, Zeb1, Vimentin, Snail and Slug have been proven to be a key role in tumor invasion and metastasis." (PMID 27893422, 2017). "A subset of 109 cases was analyzed, with a median of 13.6% of tumor cells expressing vimentin, range 2.0 – 95.3%." (PMID 29152102, 2017). "Migration refers to the behavior of the tumor cells to go to another place through deformation or movement, and vimentin promotes the deformation and movement of tumor cells." (PMID 28402270, 2017). "Vimentin dysregulation possess significant impacts on tumor growth, cellular motility, and poor prognosis." (PMID 28334027, 2017). "This cell line shows a high expression of vimentin,indicating its mesenchymal phenotype and supporting the aggressiveness of tumor growthin mice." (PMID 28430664, 2017). "The epithelial-to-mesenchymal transition (EMT), which is characterized by the down-regulation of E-cadherin and overexpression of Vimentin, is a critical biological process in tumor invasion, metastasis and chemo-resistance." (PMID 28969065, 2017). "Epithelial-to-mesenchymal transition (EMT) is a part of tumor metastasis, which is characterized by decreased epithelial marker E-cadherin and increased mesenchymal marker vimentin, is a subprocess of both tumor metastasis and drug resistance development." (PMID 28724364, 2017). "Vimentin overexpression in cancer correlates with increased tumor growth, invasion and poor prognosis." (PMID 28670517, 2017). "For vimentin, it was observed that the mean serum concentration in tumour grade 3 was highest (1350 ± 250 pg/ml) followed by grade 2 (990 + 200 pg/ml) and grade 1 (490 ± 120 pg/ml)." (PMID 28616237, 2017). "The results showed that tumor sample expressing high B7-H4 tended to have up-regulation of Vimentin and snail and downregulation of E-cadherin." (PMID 29235470, 2017). "Some of the vimentin-positive cells in the tumor-stroma interface were also positive for E-cadherin, indicating a hybrid phenotype." (PMID 28750639, 2017). "Vimentin-high clone P4B6 formed tumours which were significantly larger (P ≤ 0.01) than those formed by the other clones and parental OPCT-1, in every mouse." (PMID 28094783, 2017).